BTK (Bruton tyrosine kinase)
Diseases named in the same sentence as BTK in open-access papers (continued):
Sharing a sentence is not in itself a finding about the gene and the disease.
tumor (continued). "Although mouse models and in vitro studies have shown high correlation with BTK signaling/inhibition and its effect on tumor progression, clinical studies have been contradictory." (PMID 34063667, 2021). "Zanubrutinib (BGB-3111), a highly-specific, irreversible second generation BTK inhibitor developed in China, has greater selectivity and higher anti-tumor activity for BTK compared to ibrutinib." (PMID 33996600, 2021). "BTK and Akt/mTOR signaling have been previously shown to maintain CSCs population and drive a tumor vascularization response." (PMID 34577576, 2021). "Inhibiting the BTK mediated pathways offers a variety of benefits against both MM cancer cells themselves and the tumor microenvironment niche, which support the cancers by promoting growth and resistance to treatment." (PMID 34071917, 2021). "In this review, we summarize studies analyzing BTK signaling within the cells found in the tumor microenvironment, as well as clinical trial where BTK inhibitors are currently being used to target the tumor microenvironment as a way to combat solid tumors." (PMID 34063667, 2021). "Murine and human TAM (both in vitro generated and tumor-derived) were utilized to establish that TAM express both BTK and the NLRP3 inflammasome." (PMID 33818636, 2021). "Since PI3K is activated by a wide variety of receptor types in epithelial cancers, BTK isoforms represent a common potential therapeutic target for several tumor types." (PMID 34307353, 2021). "Taken together, ibrutinib-mediated inhibition of BTK in TAMs, MDSCs, DCs and B cells indirectly promote anti-tumor immunity by augmenting TH1 CD4 T cell response and increasing the infiltration of CD8 cytotoxic T cells and effector B cells into the TME." (PMID 34778053, 2021). "In pancreatic tumors, inhibition of the Bruton’s tyrosine kinase (BTK) signaling pathway reduces IL-35 and IL-10 expression and decreases i35-Breg cell function, suppressing tumor cell growth." (PMID 34093586, 2021). "This group found that PDAC tumor growth requires crosstalk between B cells and TAM, resulting in pro-tumor Th2-type macrophage polarization via activation of the BTK signaling cascade." (PMID 33818636, 2021). "In particular, BTK is overexpressed in TAMs and MDSCs, which regulate tumor progression, immunosuppression and angiogenesis." (PMID 34778053, 2021). "That is because BTK expressing tumor infiltrating cells within the TME include memory B cells that cooperate with memory T-cells to ensure a robust immune response to cancer cells." (PMID 33937249, 2021). "In a mouse model of PDAC, treatment with a BTK inhibitor increased the number of tumour-infiltrating CD8+ T-cells and resulted in tumour shrinkage." (PMID 34439389, 2021). "Recent studies have proposed a potential mechanism of the “protective” role of BTK as a tumour suppressor." (PMID 34645618, 2021). "And a lower expression levels of KLRG1, BTK, CCR2, SCML4 were all associated with advanced neoplasm disease stage." (PMID 34187403, 2021). "Our study also serves as a reminder that the effect of BTK in T cells should also be taken into account when using BTK inhibitors for tumor therapy." (PMID 31431692, 2020). "MDSCs are known to contribute to tumour progression, express BTK, and can differentiate into macrophages and DCs39,40 in the peripheral lymphoid organs." (PMID 32025027, 2020). "In the BTK low-expression group, metabolic pathways including glycolysis, oxidative phosphorylation, and typical tumor pathways were enriched." (PMID 32351880, 2020). "In this regard, inhibiting BTK can have this double effect in B-cell malignancies, since BTK protein is not only involved in malignant B-cell survival but is also required for the tumor-promoting effect of macrophages." (PMID 32691208, 2020).
tumor (continued). "As to BTK low-expression group, the genes were enriched in metabolic pathways, including glycolysis, oxidative phosphorylation, and typical tumor pathways." (PMID 32351880, 2020). "Transient increases in peripheral blood lymphocyte counts observed beginning in cycle 2 are consistent with the propensity for BTK inhibitors to stimulate migration of tumor cells from the lymphoid compartment into the blood." (PMID 32393328, 2020). "Our data show that ibrutinib treatment resulted in the viability of E0.2 tumour cells and decreased the BTK expression in a dose-dependent manner." (PMID 32025027, 2020). "BTK is located at the cell membrane but it can also be found in the nucleus, and it has been shown to have pro‐apoptotic and tumour suppressor functions." (PMID 31736210, 2020). "In better differentiated (G1 and G2) tumours, BTK expression was seen in 35/61 (57.38%) of the specimens." (PMID 32912025, 2020). "After that, the analysis of BTK combined with clinical characteristics was performed, and Wilcoxon rank sum test revealed that the expression of BTK in the tumor samples was significantly lower than that in the normal samples." (PMID 32351880, 2020). "In 7/31 (22.58%) of the paired cases, BTK expression in primary tumours and metastases to regional lymph nodes was similar." (PMID 32912025, 2020). "The myeloid differentiation primary response 88 (MYD88) mutation is highly prevalent in approximately 90% of patients with WM, which triggers the growth of tumor cells through BTK involved in the NF-κB pathway." (PMID 33005100, 2020). "NHWD-870 showed stronger tumor-suppressive effects than Bruton’s tyrosine kinase (BTK) inhibitor Ibrutinib in TMD8 large B cell lymphoma model." (PMID 32286255, 2020). "In poorly differentiated (G3) tumours, BTK was observed in 11/20 of the cases (55.00%), four of them with strong BTK expression." (PMID 32912025, 2020). "BTK protein has been shown to be crucial for tumor-promoting function of macrophages in different neoplasias, especially in CLL, where modulation of TAMs has been shown to be also a relevant mode of action of ibrutinib." (PMID 32691208, 2020). "Increased expression of BTK in metastases compared with primary tumours was found in 17/31 (54.84%) of the cases, and decreased expression in 7/31 (22.58%) of the cases." (PMID 32912025, 2020). "In order to better understand the tumour suppressor effects of BTK, we studied the mechanisms involved in the BTK-mediated induction of apoptosis." (PMID 30245853, 2018). "In this report, we have further characterized the role of BTK in tumour suppressor pathways by studying its relationship with p73." (PMID 30245853, 2018). "Despite its well-studied oncogenic role, it has been reported that BTK can also have tumour suppressor activity." (PMID 30245853, 2018). "BTK activity is crucial for survival and proliferation of leukemic B cells and for their interactions with cells in the tumor microenvironment." (PMID 29455639, 2018). "Given that ibrutinib shows off-target inhibition of JAK3, ITK and EGFR, it can be used to target oncogenic pathways other than BTK in tumor cells and as a T-cell modulator in combination immunotherapy." (PMID 29455639, 2018). "To investigate the consequences of BTK inhibition on tumor cells in vivo, we sequentially profiled the CLL transcriptome in 14 patients treated with single-agent ibrutinib." (PMID 29259203, 2017).
tumor (continued). "Although it has been mainly associated with B-cell malignancies, some studies have also suggested a pro-apoptotic and tumour suppressor role for BTK." (PMID 29290977, 2017). "Preclinical studies of BTK inhibitor, Ibrutinib, have shown promising results in different tumor cell lines." (PMID 29371955, 2017). "Consistent with this, IHC staining of the tumor samples using TMAs showed common BTK protein expression in the neoplastic HRS cells (72% of cases), with unusually strong expression in 8% of cases." (PMID 29340061, 2017). "In tumor infiltrating macrophages BTK was found to exert immune-inhibitory and tumor-promoting effects." (PMID 29167667, 2017). "Nevertheless, further work will be needed in order to establish, for every tumor type, the contribution of BTK-related responses versus inhibition of other kinases, either in tumor cells themselves or in the tumor stroma." (PMID 27489860, 2016). "Because in CLL patients the BTK inhibitor, ibrutinib, is known to release the tumor cells from their niches into the blood, we combined αSlamf6 treatment with administering ibrutinib." (PMID 27029059, 2016). "Ibrutinib, a BTK inhibitor, has shown encouraging anti-tumor activity against various B-cell malignancies including MCL." (PMID 27224912, 2016). "After having confirmed that this NSG xenograft model recapitulates key elements of CLL biology, we used this system to study the impact of the BTK inhibitor ibrutinib on tumor biology in vivo." (PMID 23619564, 2013). "In summary, inhibition of BTK was sufficient to substantially inhibit the supportive effect of the microenvironment on tumor proliferation and survival in vivo, most likely through inhibition of BCR and NF-κB signaling." (PMID 23619564, 2013). "BTK inhibitors, such as ibrutinib, target Bruton’s tyrosine kinase in immune cells, including myeloid cells, modulating their interaction with T cells to enhance anti-tumor responses." (PMID 40458409, 2025). "While there are no clinically approved drugs for blocking mast cell degranulation, studies have shown that inhibiting Bruton tyrosine kinase (Btk) may reduce this action among pancreatic insulinomas, leading to tumor regression." (PMID 40565098, 2025). "Acalabrutinib is a Bruton tyrosine kinase (BTK) inhibitor, and preclinical studies have suggested that combining BTK inhibition with a PD-1 blockade may enhance anti-tumor activity in PDAC." (PMID 40572765, 2025). "The combination of targeted therapeutic strategies, particularly bruton tyrosine kinase inhibitor zanubrutinib and programmed death‐1 inhibitor tislelizumab, may improve clinical outcomes and modulate the tumour microenvironment (TME)." (PMID 40268516, 2025). "Additionally, significantly elevated (p < 0.05) BTK expression was observed in GBM TSs isolated from the bulk tumor compared to its tumor-free counterpart, NHA." (PMID 41145013, 2025). "BGB-16673 is able to degrade both wild-type (WT) BTK as well as BTK with known mutations causing resistance to covalent and non-covalent BTKis, and in pre-clinical models demonstrated tumor suppression." (PMID 39941922, 2025). "Moreover, all responders remained in response and exhibited sustained reductions in the BTK protein levels in their peripheral blood or tumor tissue, indicating favorable long-term efficacy." (PMID 40719810, 2025). "Since BTK is a vital signaling node for PCNSL tumor cell genesis and development, it may be a promising target for PCNSL-targeted therapy." (PMID 40040699, 2025). "Pirtobrutinib’s reversible binding, BTK selection, high effectiveness, attractive pharmacological characteristics, and satisfactory clinical results in patients with wild-type or mutant BTK indicated it might be used to treat any BTK-driven tumor." (PMID 39994019, 2025).
tumor (continued). "Ibrutinib, as a BTK inhibitor, can inhibit the growth of tumor cells and promote apoptosis by regulating the tumor microenvironment, reducing the secretion of chemokines and proinflammatory factors, and downregulating the expression of anti-apoptotic proteins bcl-2 family." (PMID 38982482, 2024). "As the combination of rituximab and lenalidomide may enhance tumor susceptibility to acalabrutinib, further preclinical studies to find subset of GCB-type DLBCL that may be dependent on the BTK signaling may be needed." (PMID 38555311, 2024). "The ibrutinib-mediated modulation of the TME involves disrupting oncogenic signaling axes and inhibiting growth-supportive cytokines and growth factors, highlighting the dynamic interplay between the TME and tumor cells in driving resistance mechanisms to BTK inhibitors." (PMID 39062757, 2024). "Thus, functional inhibition of BTK in primary CLL cells strongly reduces BCR- plus chemokine-controlled retention of leukemic B cells in their protective tumor microenvironment." (PMID 38469232, 2024). "Here, we could demonstrate that BTK inhibition by AVL-292 impaired tumor growth and its vascularization in tumor xenografts." (PMID 36612306, 2023). "Moreover, abrogation of BTK activity inhibited tumor progression in our study in terms of proliferation and vascularization in vitro and in vivo." (PMID 36612306, 2023). "Altogether, our findings suggest a dual role of BTK during tumorigenesis and tumor progression." (PMID 36612306, 2023). "So far, the exact mechanisms for BTK-p80 and BTK-p65 –dependent tumor cell growth are unknown and might involve pathways different from those reported in hematopoietic cells." (PMID 36612306, 2023). "In addition to morphological changes, we found a dramatic decrease in tumor sphere formation under BTK inhibition in all the analyzed cell lines, which was accompanied by a significant reduction in the expression of the cancer stemness marker ALDH1A1." (PMID 37685940, 2023). "BTK-inhibition targets tumor apoptosis by disturbing PI3K/Akt signaling." (PMID 37655217, 2023). "Firstly, it shows effects against CLL cells, which could sensitize the tumor cells to BTK inhibitors." (PMID 38140397, 2023). "In order to investigate whether BTK influences the EMT by interfering with the pro-tumorigenic cytokine release from tumor cells, UDSCC1, -5, and -6 cells were cultured under 3D conditions and either left untreated or treated with AVL-292 for 72 h." (PMID 37685940, 2023). "Abrogation of BTK activity inhibited tumor progression in our study." (PMID 36612306, 2023). "Inhibition of BTK in the pancreatic TME reduced tumor growth and enhanced antitumor activation." (PMID 36816959, 2023). "Taken together, these data suggest BTK’s double-pronged role in cancer cell proliferation on the one side and tumor-driven angiogenesis on the other, both events acting ultimately toward a sustained tumor growth." (PMID 36612306, 2023). "Collectively, inhibition of ERK, AKT, and NF-κB signaling followed by BTK inhibition could contribute as important mechanisms of the anti-tumor effects exerted by tirabrutinib in TMD8." (PMID 36897912, 2023). "In contrast, a CLIA-certified drug sensitivity assay of an organoid culture derived from the patient’s tumor identified several therapeutic choices, including Bruton’s tyrosine kinase (BTK) inhibitor ibrutinib, as well as the EGFR inhibitors afatinib and erlotinib." (PMID 37202426, 2023). "In the future, we will also need to further investigate the combination therapy of BTK inhibitors with other anti-tumor drugs in order to increase the anti-tumor efficacy and prevent the adverse reactions that are caused by non-selective inhibition by BTK inhibitors." (PMID 36903645, 2023). "Interestingly, LCK showed a similar pattern of upregulation in DLBCL tumor samples as BTK and SYK, both of which drive the BCR signaling pathway and are therapeutic targets in B-cell malignancies." (PMID 36711753, 2023).
tumor (continued). "BTK inhibition resulted in a dose-dependent reduction in tumor formation." (PMID 36612306, 2023). "Thus, the objective of this in vitro and in vivo study was to analyze the anti-tumor mechanism of tirabrutinib, a highly selective BTK inhibitor in ABC-DLBCL, using phosphoproteomic and transcriptomic techniques." (PMID 36897912, 2023). "In contrast, in tumor cells this region is less methylated and therefore could be more active, resulting in an upregulation of BTK-p80 and BTK-p65 protein expression under cancerogenic conditions." (PMID 36612306, 2023). "The results showed that in univariate analysis, T, N, M, tumor stage, and the expression level of BTK were significantly correlated with the prognosis of patients ( ∗P < 0.05), while in multivariate analysis, only N and BTK were significantly correlated with the prognosis of patients ( ∗P < 0.05)." (PMID 37638060, 2023). "Neratinib and erlotinib, both targeting the EGF receptor, were also active (SPM score 87.1 and 89.8, respectively) suggesting this patient’s tumor may be dependent on BTK and/or EGFR signaling." (PMID 37202426, 2023). "Importantly, tumor xenografts revealed a significant reduction in desmin-positive pericytes upon BTK inhibition, indicating a strong reduction in tumor-induced vascularization." (PMID 36612306, 2023). "Additionally, our data demonstrate that even cells characterized by a lower response to BTK inhibition reveal impaired tumor growth and angiogenesis in vivo induced by BTK activity abrogation." (PMID 36612306, 2023). "Concomitant BTK inhibition may subvert the upregulation of alternative BCL2 family proteins by the tumor microenvironment, and combination trials have demonstrated frequent deep remission in CLL and MCL." (PMID 35659041, 2022). "BTK affects cell growth, survival, and migration of tumor cells via activation of CXCR4." (PMID 36294458, 2022). "Finally, activation of the Bruton tyrosine kinase (BTK) in B-cells has been shown to foster reprogramming of tumor infiltrating macrophages towards a M2 phenotype thus impairing CD8+ T-cell anti-tumor responses and supporting PDAC growth." (PMID 35359944, 2022). "For example, therapy with the covalent, orally bioavailable BTK inhibitor ibrutinib, one of the first targeted agents in CLL, leads to a rapid shrinkage of tumor mass in lymphoid organs, caused in part by the redistribution of CLL cells from the tissue into the bloodstream." (PMID 35883678, 2022). "This disorder triggers tumor growth by activating NF-κB signaling via BTK." (PMID 36183125, 2022). "Similarly, ibrutinib - another BTK inhibitor - combined with gemcitabine slowed tumor growth of orthotopic PDAC in a T-cell dependent manner." (PMID 35359944, 2022). "Additionally, BTK is present in other cells that contribute to regulation of tumor microenvironment including dendritic cells, macrophages, myeloid derived suppressor cells and endothelial cells." (PMID 36294458, 2022). "Then, we conducted western blotting to measure p-BTK expression in tumor tissues." (PMID 36588692, 2022). "CPVL may promote human tumor progression by inhibiting STAT1 pathway through interacting with BTK/p300 axis." (PMID 36479092, 2022). "Similarly, the clinically approved Bruton Tyrosine Kinase (BTK) inhibitor, Ibrutinib, has been shown to exert potent anti-fibrotic and anti-tumour activities in mouse models of PDAC." (PMID 35929603, 2022). "Given the critical role of BCR in the proliferation and survival of cancer cells in a variety of B-cell malignancies, disrupting BCR signaling pathways involved in tumor cell survival through targeting its components such as BTK seems to be a good therapeutic approach." (PMID 36294458, 2022). "BTK regulates B-cell survival, and also plays a critical part in signaling of Toll-like receptor and chemokine receptor, which can regulate cell migration and the tumor microenvironment." (PMID 36588692, 2022).